IGF1 (insulin like growth factor 1)
Diseases named in the same sentence as IGF1 in open-access papers (continued):
Sharing a sentence is not in itself a finding about the gene and the disease.
liver cirrhosis (45 papers, 2005 to 2026). "Another IGF-1 deficiency condition, in this case in adults, is liver cirrhosis, where decreased IGF-1 serum levels were found in these patients." (PMID 32046737, 2020). "A lower serum level of IGF-1 was associated with more advanced stages of liver cirrhosis (p < 0.05) and cancer stages (p < 0.001)." (PMID 30064393, 2018). "In patients with liver cirrhosis, a condition of IGF1 deficiency is thought to result from the reduced synthetic capability of damaged hepatocytes, as supported by the correlation between IGF1 levels and albumin in cirrhotic patients." (PMID 25225571, 2014). "However, during the last decade, our research team has disclosed the causal link between IGF-1 deficiency and the severe malnutrition syndrome associated to liver cirrhosis progression." (PMID 32046737, 2020). "Studies have found that growth hormone resistance and low insulin-like growth factor-1, thyroid dysfunction, and other problems are common in patients with liver cirrhosis, which will affect negatively its prognosis." (PMID 36193202, 2022). "A lot of studies have demonstrated that liver cirrhosis by itself is responsible for decreased serum concentrations and tissue expression of IGF-1 protein, that have been more pronounced in patients with HCV infection than those without." (PMID 36374927, 2022). "The administration of IGF-1 has been shown to preclude fibrosis and ameliorate liver function in a rat model of liver cirrhosis and recovery of heart functions and inhibit myocardial fibrosis in a mouse model of dilated cardiomyopathies." (PMID 33807089, 2021). "In liver cirrhosis, decreased levels of testosterone and IGF-1 contribute to increased myostatin expression and impaired protein synthesis." (PMID 32731496, 2020). "Low serum levels of IGF-1 are common features in patients with diseased liver compared to healthy people and in liver cirrhosis." (PMID 30064393, 2018). "In developed liver cirrhosis, decreased concentrations of IGF1 were observed, in comparison with healthy individuals." (PMID 29702590, 2018). "Then, rSVIGF1 therapeutic efficacy was studied in rats, in which liver cirrhosis was induced by carbon tetrachloride (CCl4) inhalation and showed that the hepatic levels of IGF1 and IGFBP3 were higher in rSVIGF1-treated rats than in control cirrhotic animals." (PMID 29702590, 2018). "Regarding CTP score, IGF-1 levels decreased significantly with more advanced stage of liver cirrhosis (p < 0.05)." (PMID 30064393, 2018). "The availability of animal models for experimental liver cirrhosis (carbon tetrachloride, thioacetamide, bile duct ligation, d-galactosamine, etc.)helped to better clarify the role of IGF1 in this pathology." (PMID 29702590, 2018). "In each etiology of liver cirrhosis, similar IGF system disturbances are observed, namely GH resistance and IGF1 deficiency, with a variety of resulting metabolic complications." (PMID 29702590, 2018). "Similar changes in IGF1 concentrations, depending on the clinical stage of liver cirrhosis, are also described in children." (PMID 29702590, 2018). "Decreased inflammation, reduced HSC activation and the trophic effect of IGF-1 on hepatocytes attenuates liver cirrhosis." (PMID 26152281, 2015). "As expected, apoptosis of enterocytes was increased during the development of liver cirrhosis via regulating Bax and Bcl-2, and external administration of IGF-1 reduced enterocytic apoptosis in liver cirrhotic rats through regulating Bax and Bcl-2." (PMID 26152281, 2015). "Previous studies showed that external administration of insulin-like growth factor 1 (IGF-1) improved intestinal barrier function in liver cirrhosis." (PMID 26152281, 2015). "Within the context of liver cirrhosis, several studies have highlighted the strong correlation between basal and stimulated IGF-1 serum levels and the degree of liver failure, as expressed by the Child Pugh or MELD-score, serum albumin or INR." (PMID 26186540, 2015).
liver cirrhosis (continued). "IGF-1 is reduced in liver cirrhosis patients, and negatively correlated with MELD score and liver cirrhosis severity." (PMID 26152281, 2015). "The trophic effect of IGF-1 on hepatocytes also possibly contributes to the improvement of liver cirrhosis." (PMID 26152281, 2015). "External administration of IGF-1 restored IGF-1 level of liver cirrhosis and reduced the levels of serum ALT and AST, which implicated that IGF-1 protected hepatocytes from damaging in liver cirrhosis." (PMID 26152281, 2015). "Our data further supports IGF-1 as a potential therapy for liver cirrhosis and enriches our knowledge about IGF-1 on intestinal barrier dysfunction." (PMID 26152281, 2015). "Our data confirm that external administration of IGF-1 can reduce hepatocellular injury and attenuate liver cirrhosis, which is consistent with that of the previous studies." (PMID 26152281, 2015). "IGF-1 also plays a critical role in intestinal health, where it promotes intestinal mucosal hyperplasia, improves barrier function, and reduces bacterial translocation in conditions such as severe burns and liver cirrhosis." (PMID 41041670, 2025). "It has been demonstrated that IGF-1 could improve the rat model of liver cirrhosis by reducing oxidative mitochondrial damage, correcting impaired mitochondrial function, and reducing caspase activity." (PMID 38492309, 2024). "Additionally, insulin-like growth factor-1 alleviates liver cirrhosis by inducing cell senescence and inactivating hepatic stellate cells." (PMID 39502571, 2024). "A study reported that low levels of insulin-like growth factor 1 in patients with advanced liver cirrhosis may aggravate bone remodeling and maintenance of bone mass in elderly patients, causing fragility fractures." (PMID 33243187, 2020). "It was proven, by numerous studies, that treatment with IGF1 can be beneficial in liver cirrhosis." (PMID 29702590, 2018). "IGFBP3 serum levels, such as IGF1, were related to severity of liver cirrhosis." (PMID 29702590, 2018). "Lastly, IGF-1 deficiency, present in liver cirrhosis, represents a negative factor for the magnitude and proportion of liver damage, since the livers from IGF-1-deficient mice (Hz Igf1+/−) show a clear vulnerability to oxidative damage and inflammation." (PMID 28472963, 2017). "HCC was associated with lower serum IGF1 and IGFBP3 levels compared to liver cirrhosis (p = 0.037)." (PMID 29113370, 2017). "Moreover, the IGF-1 level of liver cirrhosis group was reduced compared with that of the control group, which indicated IGF-1 insufficiency in liver cirrhosis." (PMID 26152281, 2015). "As liver is the major synthesis site for IGF-1 and growth hormone (GH) receptor, reduced IGF-1 in liver cirrhosis could be explained by reduced liver function for synthesizing IGF-1 and impaired GH response in liver." (PMID 26152281, 2015). "The cytoprotective effect of prostaglandin produced by COX-2 might be one of the mechanisms of IGF-1 improving intestinal barrier function in liver cirrhosis." (PMID 26152281, 2015). "The cytoprotective effect of prostaglandins produced by COX-2 might be one of the mechanisms of IGF-1 improving intestinal barrier function in liver cirrhosis." (PMID 26152281, 2015). "The changes of IGF-1 in serum during the development of rat liver cirrhosis were also evaluated." (PMID 26152281, 2015). "In liver cirrhosis IGF-1 level would be decreased while growth hormone would be increased." (PMID 23599716, 2013). "Liver cirrhosis is a state accompanied by a decrease in IGF-1 and progression of the disease." (PMID 23599716, 2013). "Replacement therapy with IGF-1 in liver cirrhosis patients requires daily doses of 1.5 to 2 mg." (PMID 19344517, 2009).
liver cirrhosis (continued). "By decreasing the liver synthetic function and by progressive loss of growth hormone receptors on hepatocytes, synthesis and concentration of IGF-1 could also be reduced, especially in advanced stages of liver cirrhosis, which consequently could lead to bone deterioration, as noted in our study." (PMID 38472981, 2024). "Moreover, LPS penetrating defect intestinal barrier in liver cirrhosis could also reduce GH releasing in pituitory, IGF-1 synthesis and release in liver would be reduced consequently." (PMID 26152281, 2015). "Serum IGF-1 levels were decreased in the development of rat liver cirrhosis, and external administration of IGF-1 restored serum IGF-1 levels." (PMID 26152281, 2015). "Instead, the result of the study in patients with liver cirrhosis showed that carnitine supplementation did not affect the IGF1 levels also Circulating IGF‐I was not affected by LC treatment on porcine fetal." (PMID 37078370, 2023). "Here, advanced-stage liver cirrhosis (CHILD B/C) resulted in lower levels of IGF-1 compared to patients without liver cirrhosis or in CHILD A stage." (PMID 30064393, 2018). "Different values of lowered serum concentration of both IGFs were proposed as a negative prognostic factor in patients with liver cirrhosis (IGF1: 13, 30 ng/mL; IGF2: below 200 ng/mL)." (PMID 29702590, 2018). "The depletion circulating levels of IGF-1 in advanced liver cirrhosis is well documented; however, this does not occur in acute damage." (PMID 28472963, 2017). "Our explanation is that IGF-1 reduces portal LPS level through improving intestinal barrier function, reduced LPS alleviates hepatic stellate cells (HSC) activation which is a key player in the development of liver cirrhosis." (PMID 26152281, 2015). "The etiology of liver cirrhosis did not influence basal IGF-1 levels, but a significant inverse correlation between the degree of liver dysfunction assessed by the MELD score and IGF-1 values before LT was observed (r coefficient = -0.3616; p = 0.0456)." (PMID 26186540, 2015). "IGF1 values of <30 ng/mL were a negative prognostic factor in patients with liver cirrhosis." (PMID 29702590, 2018). "However, the mechanism of IGF-1 on intestinal barrier in liver cirrhosis is not fully elucidated." (PMID 26152281, 2015).
Ewing sarcoma (43 papers, 2005 to 2025). A small round cell tumor that lacks morphologic, immunohistochemical, and electron microscopic evidence of neuroectodermal differentiation. "In a study on Ewing sarcoma, high levels of both circulating IGF-1 and IGFBP-3 in the serum were associated with improved OS in patients treated with chemotherapy." (PMID 37510722, 2023). "It was shown that the high level of IGF-1 in the serum of patients with Ewing sarcoma was correlated with a lower risk of tumor progression." (PMID 36713521, 2022). "High baseline IGF1 was counterintuitively associated with improved event-free survival (EFS) in Ewing sarcoma patients." (PMID 33260481, 2020). "In Ewing sarcoma, IGF2BP3 loss promotes the downregulation of IGF1R and a decreased biological response to IGF1." (PMID 40442778, 2025). "Previous analysis of autocrine signaling circuits in Ewing sarcoma identified the activity of IGF1 (IGF2)/IGF1R signaling in both Ewing sarcoma cells and patient tissues." (PMID 38906855, 2024). "These inhibitors can be potentially used in Ewing sarcoma treatment, given the fact that the IGF1/IGF-1R signaling pathway plays a significant role in Ewing sarcoma malignancy." (PMID 37830183, 2024). "Examining the IGF-1 family revealed an increase in the gene and protein level of IGF-1R in bone tumors of osteosarcoma and Ewing sarcoma compared to tumor margins as well as the circulating level of IGF-1, IGFBP-, and IGFBP-3 in these patients." (PMID 36713521, 2022). "Regarding the stimulating or inhibiting role of the IGF-1 axis in the pathogenesis of Ewing sarcoma, the evidence is conflicting." (PMID 36713521, 2022). "It was shown that inhibition of EWS::FLI1protein was associated with reduced IGF-1/IGF-1R signaling and induced Ewing sarcoma apoptosis and death that is postulated to be related to the interaction of IGF-1R and focal adhesion kinase (FAK)." (PMID 36713521, 2022). "EWS-FLI1 represses the transcription of IGFBP3, while favoring the transcription of IGF1, which is a critical step in Ewing sarcoma tumorigenesis." (PMID 34440844, 2021). "On the other hand, mitogenic stimulation of Ewing sarcoma cells by treatment with Insulin-like Growth Factor (IGF)-1 inhibits the interaction between Sam68 and pncCCND1_B and leads to an increase in cyclin D1 transcription." (PMID 32722129, 2020). "A switch between the two complexes can be promoted by the IGF-1 signaling pathway, which is a critical contributor to malignant transformation and chemotherapy resistance of Ewing sarcoma." (PMID 32722129, 2020). "Ewing sarcoma is a rare cancer that is characterized by a translocation that increases the bioactivity of IGF1." (PMID 33260481, 2020). "In Ewing sarcoma, lower IGF-1 circulating levels were found in patients with metastatic disease, while in a cohort of 57 patients, a relationship between high IGF-1R and IGF-1 expression and favorable prognosis was found." (PMID 28545426, 2017). "Silencing of pappalysin-1 resulted in accumulation of IGFBPs and reduced bioactive IGF-1 in Ewing sarcoma cell secretome, leading to suppression of IGF signaling." (PMID 29321818, 2017). "It is an appealing strategy using BET inhibitors to block the IGF1 autocrine mechanism in Ewing sarcoma patients with high IGF1R expression, which is expected to spare normal tissues from toxicity of anti-IGF1R therapy." (PMID 27259270, 2016). "The IGF-1 pathway is also critical for the pathogenesis and proliferation of Ewing sarcomas and directly regulated by EWS/FLI1." (PMID 27539223, 2016). "The potent and universal blockade of IGF1 expression by BET inhibitors in Ewing sarcoma was unexpected." (PMID 27259270, 2016). "The resultant IGF1 autocrine loop is essential to sustain adequate activation of the IGF1R/PI3K/AKT signaling pathway in Ewing sarcoma." (PMID 27259270, 2016). "Activation of the IGF1R pathway in Ewing sarcoma is critically sustained by IGF1 produced by tumor cells." (PMID 27259270, 2016).
Ewing sarcoma (continued). "The IGF-1 pathway is functionally important for the pathogenesis and progression of Ewing Sarcoma and the fusion protein EWS/FLI1 has been shown to downregulate the expression of IGFBP3 in Ewing sarcoma cell lines." (PMID 27539223, 2016). "Repression of autocrine IGF1 by BET inhibitors led to significant inhibition of the IGF1R/AKT pathway critical to Ewing sarcoma cell proliferation and survival." (PMID 27259270, 2016). "Insulin-like growth factor 1 (IGF1) reputedly opposes chemotoxicity in Ewing sarcoma family of tumor (ESFT) cells." (PMID 23091403, 2012). "EWS-FLI1 fusion protein, the hallmark of Ewing's sarcoma, downregulates insulin-like growth factor binding protein 3, IGFBP3, and upregulates IGF-1 expression resulting in enhanced IGF1R." (PMID 21494688, 2011). "Here we show that treatment with rapamycin activated PP2A and concurrently suppressed IGF-1 stimulated phosphorylation of Erk1/2 in human Ewing sarcoma (Rh1) and rhabdomyosarcoma (Rh30) cells." (PMID 20485667, 2010). "Here we show that rapamycin inhibited the basal or insulin-like growth factor 1 (IGF-1)-induced motility of human Ewing sarcoma (Rh1) and rhabdomyosarcoma (Rh30) cells." (PMID 20485667, 2010). "Previous studies suggested insulin-like growth factor 1 (IGF1) as one of the key growth factors of Ewing tumours." (PMID 15685229, 2005). "Incidence rates of Ewing sarcoma and endogenous IGF-1 levels peaked around puberty." (PMID 35680570, 2022). "In Ewing sarcoma patients treated with figitumumab and R1507 pretreatment serum levels of IGF1 were associated with increased survival but not with drug response." (PMID 34440844, 2021). "Furthermore, those functional studies showed that rapamycin inhibited the basal or IGF-1-induced motility of Ewing sarcoma (Rh1) and ARMS (Rh30) cell lines." (PMID 29861864, 2018). "It is worth noting that the IGF1R-low line A673 had the highest IC50 value among these lines, thus supporting the hypothesis that the IGF1 autocrine loop is a key target of BET inhibitors in Ewing sarcoma." (PMID 27259270, 2016). "Hence, BET proteins are essential to sustain the IGF1 autocrine mechanism in Ewing sarcoma, suggesting an alternative approach to block this important pathway in tumors without perturbation of IGF1 signaling in normal tissues." (PMID 27259270, 2016). "It has also been shown that EWS-FLI1, the genetic hallmark of Ewing sarcoma, is only capable of transformation in the presence of IGF-1R and, more recently, that this fusion product directly affects IGF-1R signalling either by downregulating IGFBP3, increasing IGF1 promoter, or both." (PMID 21647361, 2011). "IGF-1R signaling has an effect on endogenous IGF-1, and the fusion gene EWS-FLI1 is present in Ewing sarcoma." (PMID 35680570, 2022). "In-depth studies have found that the insulin-like growth factor-1 (IGF-1) / IGF-1 receptor (IGF-1R) system plays an important role in the occurrence and development of Ewing’s sarcoma." (PMID 34996476, 2022). "Data from the current study showed over-expression of IGF-1R, IGF-1, IGFBP-1, and 3 in local tumor tissues and serum of patients with Ewing sarcoma." (PMID 36713521, 2022). "As a result, Ewing sarcoma cells are characterized by a unique autocrine loop, mediated by the IGF1R/IGF1 axis, which strongly contributes to cellular malignancy." (PMID 34440844, 2021). "BET inhibitors inhibited autocrine IGF1 action and activation of the IGF1R/Akt pathway in Ewing sarcoma cells." (PMID 34440844, 2021). "Based on Ewing sarcoma model and EWS-Fli translocation, leading to dysregulation of insulin growth factor 1 (IGF1) receptor and dependence on IGF1, humanized monoclonal antagonist IGF1 receptor (IGF1R) antibodies have been developed." (PMID 28491276, 2017). "Because IGF1 is a direct target gene of EWS-FLI1, this autocrine loop is largely driven by EWS-FLI1 in Ewing sarcoma." (PMID 27259270, 2016).